MMP2 (matrix metallopeptidase 2)
Diseases named in the same sentence as MMP2 in open-access papers (continued):
Sharing a sentence is not in itself a finding about the gene and the disease.
cancer (continued). "One study established that overexpression of CLDN-1 induces MMP-2 in SNU-354, -423 and -449 HCC cells resulting in increased invasion and migration of the cancer cells compared to the normal liver cells and other CLDN-1 expressing HCC cells such as SNU-398 and SNU-475." (PMID 31952355, 2020). "In this study, we demonstrated that the metabolite secretions of GG, M3 and YYC-3 suppressed VEGFA expression and secretion, and limited the expression and secretion levels of MMP2 and MMP9; suggesting that the inhibition of VEGF-MMP signalling pathway is suppressing cancer cell metastasis." (PMID 33228670, 2020). "In cancer development, BRD4 was a stimulator for the expression of cell proliferation related genes, such as c-Myc, CyclinD1 and CDK4, as well as cell migration related genes, such as MMP-2 and MMP-9." (PMID 32640974, 2020). "Moreover, since Ezrin has been shown to modulate Matrix Metalloproteinases activity in cancer cells, we examined the effect of the two diterpenes on either MMP-9 or MMP-2 activity." (PMID 33003361, 2020). "Remodelling of extracellular matrix play particularly important role in creating microenvironment permissive for metastatic cancer cells: activation of fibroblasts/myofibroblasts, reorganization of collagen fibers, and change in expression of ECM-remodelling enzymes such as MMP2, MMP9 and LOX43,45." (PMID 32286443, 2020). "Therefore, reducing the expression of MMP-2 and MMP-9 or its upstream regulatory signaling pathways is essential for the treatment of malignant tumors." (PMID 32922544, 2020). "We found that AIM suppressed NF-κB activation induced by TNF-α in MCF-7 cells, and the upregulation of NF-κB-regulated genes (COX-2; MMP-2, MMP-9, and VEGF) involved in cancer cell proliferation (COX-2, C-myc, Cyclin-D1), and invasion, adhesion, and angiogenesis (MMP-2, MMP-9, ICAM-1, VEGF)." (PMID 32455624, 2020). "Therefore, we evaluated the changes in MMP2 and MMP9 expression and activity in the cancer cells by western blotting and gelatin zymography assays, respectively, under the same conditions used in the migration/invasion assays." (PMID 33371405, 2020). "Macrophage colony-stimulating factor (M-CSF), matrix metalloproteinase-2 (MMP-2) and its specific tissue inhibitor (TIMP-2) may play an important role in the pathogenesis of cancer disease." (PMID 30820752, 2020). "Consistently, our correlation analyses confirmed that the normalised BRD4 and MMP2 expression levels were correlated in cancer tissues but not in non-cancer tissues." (PMID 32499570, 2020). "In contrast, MMP2 gelatinase activity exhibited high basal levels in supernatants from MSCs alone and was not significantly elevated in supernatants isolated from the MSC-PC9 cancer cell co-cultures." (PMID 33119681, 2020). "Fucoidan derived from U. pinnatifida sporophylls inhibit hypoxia in cancer cells through nuclear translocation, activity of HIF-1α and reduction in the levels of phosphorylated-PI3K (p-PI3K), p-Akt, p-mTOR, p-ERK, NF-κB, MMP-2, and MMP-9, but increased TIMP-1 levels." (PMID 32354032, 2020). "In addition, VEGFα, MMP2, ADAM12 and Vim, which are produced by cancer cells, have been reported to disrupt vascular integrity." (PMID 32537867, 2020). "MMP2 and MMP-9 are matrix metalloproteinases that promote the invasion of cancer cells." (PMID 32550915, 2020). "It is possible that the upregulated GRP78 may promote MMP-2, MMP-9 and uPA expression to increase ECM degradation, leading to cancer cell invasion." (PMID 32393740, 2020). "However, studies of MMP-2 and MMP-2 inhibitors have mainly focused on cell migration and many cancers, and few studies of the effects of MMP-2 or MMP-2 inhibitors on bone healing have been reported." (PMID 33553142, 2020). "In addition to EMT, NOB can inhibit MMP-2 and MMP-9 expressions to suppress the metastasis of cancer cells." (PMID 32380783, 2020).
cancer (continued). "Interestingly, MMP-14 has been proposed as an activator of latent MMP-2 in conjunction with tissue inhibitors of metalloproteinase 2 (TIMP-2) for degradation of extracellular matrix and promotion of cancer invasion and metastasis." (PMID 32848608, 2020). "Activation of MMP-2 and MMP-9 is related to PC progression through invasion of cancer cells." (PMID 32349276, 2020). "Apart from that, CD44 also plays an important role in MMP-2 and MMP-9 activation through the binding of proteolytically active MMP-2 and MMP-9 isoforms to the membrane and promoting the cleavage of latent TGF-β, which led to invasion and angiogenesis across various cancer models." (PMID 33335857, 2020). "The present review discusses the involvement of two MMPs, MMP-2 and MMP-7, in cancer pathogenesis." (PMID 32751899, 2020). "MMP2-targeted JP3 was finally determined to be the best anti-cancer peptide without detectable side effects in animal models, showing a therapeutic efficacy." (PMID 32576271, 2020). "Davidson and co-workers found MMP-2 mRNA almost exclusively in cancer cells, and found that it was lacking in preinvasive dysplastic lesions and healthy tissue." (PMID 32751899, 2020). "However, in various cancers, aberrant STAT5 signalling promotes the expression of target genes, such as cyclin D, Bcl-2 and MMP-2, that result in increased cell proliferation, survival and metastasis." (PMID 32872372, 2020). "MMP-2 and MMP-9 have been observed in various types of human carcinoma to facilitate metastasis." (PMID 32626656, 2020). "Interestingly, MMP2, MMP7, MMP23B, MMP27 and MMP28) are significantly down-regulated in seven to nine cancer types." (PMID 31200666, 2019). "As opposed to our findings when studying diffusion-dominated cancer cell movement, we observed that invasion was no longer possible for the same range of MMP-2 production rates." (PMID 30903592, 2019). "In addition, the invasion and aggressiveness of cancer cell lines was significantly decreased by CM-MSC; this was translated by a decrease in MMP-2, MMP-9, and CA-125 mRNA expression, and an increase in TIMP 1, 2, and 3 mRNA expression." (PMID 31351482, 2019). "MiR-203 is a cancer suppressor that interacts with different genes involved in hepatocarcinogenesis, such as EZH2 and BMI1, SURVIVIN, RASAL2, ADAM9, and MMP2." (PMID 31073374, 2019). "These molecules could indeed attract cancer cells to intrapancreatic nerves, upregulate MMP–2 and MMP–9 expression along the axons to facilitate extracellular matrix breakdown and cancer progression." (PMID 31248001, 2019). "MMP-2 and MMP-9, which are key factors in cancer metastasis, were affected by RBP4 overexpression." (PMID 31212896, 2019). "miR-29c has been investigated in a number of cancer settings with a number of confirmed targets identified, including integrin beta 1 (ITGB1) and matrix metalloproteinase 2 (MMP2) for which luciferase reporter assays confirming direct targeting of miR-29c has been previously reported." (PMID 31201347, 2019). "Expression of MMP2 and MMP9 is correlated with cancer progression and metastasis." (PMID 31106200, 2019). "MMP-2 and MMP-9 are highly-expressed in malignant tumors, and have been shown to be involved in degradation of the ECM, a crucial component of the basal membrane, which consequently leads to cancer metastasis." (PMID 31783709, 2019). "Cancer cell invasion is mediated by breakdown of the basement membrane, a process dependent on extracellular matrix degradation by the matrix metalloproteinase (MMP) enzymes MMP-2 and MMP-9." (PMID 31588240, 2019). "If MMP-2 and MMP-9 participate in leptin-dependent migration via FAK activation, their secretion must be controlled by a similar signaling pathway that controls migration of cancer cells." (PMID 31671408, 2019).
cancer (continued). "Moreover, we unveiled a novel mechanism of FOXM1c in regulating cancer invasion and migration, that is, FOXM1c transcriptionally regulated IRF1 by directly binding to its promoter region, and IRF1 further modulated MMP2/9 expression." (PMID 30485581, 2019). "Our previous investigations performed on GC, CC and EC patients have revealed that the serum concentrations of MMP-2 and TIMP-2 in cancer patients were statistically lower in comparison to healthy subjects and all these differences reached statistically significance." (PMID 30719232, 2019). "Therefore, Matrix Metalloproteinases (MMPs), in particular MMP-2 and MMP-9, are involved in cancer metastasis, and inhibitors of MMP are studied as possible antitumor tools." (PMID 31543862, 2019). "MMP-2 and MMP-9 can be activated through the urokinase plasminogen activator (uPA)/plasmin cascade, and both serve as important molecules in terms of facilitating invasion and metastasis of cancer cells." (PMID 31783709, 2019). "Among the MMPs, MMP-2 and MMP-9 have been involved extensively in facilitating cancer metastasis." (PMID 31658635, 2019). "This framework accounts for the spatiotemporal evolution of mesenchymal- and epithelial-like cancer cells, membrane-type-1 matrix metalloproteinase (MT1-MMP) and the diffusible matrix metalloproteinase-2 (MMP-2), and for their interactions with the extracellular matrix." (PMID 30903592, 2019). "Both MMP-2 and MMP-9 are vital mediators of the invasion in many cancer types." (PMID 29419740, 2018). "Then, we tested the expression level of MMP2 and MMP9, which are essential for cancer metastasis." (PMID 29642915, 2018). "MMP-2 was found to be commonly constitutively expressed in various tissues including malignant neoplasms, rather than as part of an initial response to invasion." (PMID 30401729, 2018). "Thus, considering the earned results, it seems that inhibition of angiogenesis through down-regulation of MMP-2, MMP-9, and VEGF in HNSCC is one the possible mechanisms of cancer treatment." (PMID 30233776, 2018). "The MMP-2 and MMP-9, key factors in cancer metastasis, were induced by RBP4 overexpression." (PMID 29642915, 2018). "After S100A4 knockdown in cancer cells, certain genes that inhibit proliferation and migration (e.g., FAM107B and E-cadherin) were upregulated, while those genes that normally promote proliferation and migration (e.g., NF-κB, p65 and MMP2) were downregulated." (PMID 29342841, 2018). "IL-6-induced transcriptional factor or cytokines, such as c-Myc and vascular endothelial growth factor, initiate and promote cell growth by triggering proliferation, and MMP2 and MMP9 proteins induce cell migration, which is closely related to metastasis and invasiveness in human cancer." (PMID 30202238, 2018). "We found that andrographolide exhibited anti-migration and anti-invasive ability against cancer metastasis via inhibition of MMP2 activity rather than affected MMP-9 and EMT." (PMID 30359388, 2018). "Our previous reports also have established that a number of matrix metalloproteinases (MMPs), known to be upregulated in cancers, including OSCC, bind and interact with specific MMPs in biochemical and biologic systems: MMP2 with BSP; MMP3 with OPN; MMP9 with DMP1; and MMP20 with DSPP." (PMID 30002682, 2018). "MMP2 and MMP9 have been shown to be upregulated in angiogenic lesions, and angiogenesis is required for the growth and metastasis of invasive tumors and plays an important role in the control of cancer progression." (PMID 30154451, 2018). "Our data also show that MMP2 and MMP9 play a huge role in the migration of cancer cells." (PMID 30241395, 2018). "Additionally, Wnt/β-catenin pathway is also correlated with the expression and activity of MMP-2 and MMP-9, co-contributing to cancer progression." (PMID 30484490, 2018).
cancer (continued). "Although significant insights on the role of MMP2, MMP3, and MMP9 in OSCCs and other cancers have been gained, the full functional/mechanistic role of DSPP-MMP20 partnering and interaction in the biology of OSCC and other cancers is just beginning to be explored." (PMID 30002682, 2018). "MMP2, IGF2, DCN, LUM and TWIST are involved in proteoglycans in cancer pathway." (PMID 30576338, 2018). "The gelatinase activity of MMP-2 and MMP-9 is closely related to the invasiveness of cancer cells." (PMID 30210348, 2018). "The matrix metalloproteinase-2 (MMP-2), MMP-9 and urokinase-PA (u-PA) are responsible for the degradation of extracellular matrix components and play important roles in the process of cancer invasion and metastasis." (PMID 29636641, 2018). "MMP-2 and MMP-9 are commonly expressed in many malignant tumors." (PMID 30960968, 2018). "However, it appears that MMPs are important enzymes involved in local attack and metastatic PTC cancer, being reported in several studies related to different members of the MMP family, including MMP-1, MMP-2, MMP-7, MMP-9, MMP-10, MMP-13, MMP-14 and MMP-15." (PMID 30509240, 2018). "They focused on AKT-mediated MMP-2 and MMP-9 to explain FOXC2-related cancer aggressiveness." (PMID 29801468, 2018). "In addition, combined andrographolide with radiation appeared to be more effective in reducing MMP-2 expression, and this effect was accompanied by suppression of ERK activation that inhibits cancer cell migration and invasion." (PMID 30359388, 2018). "MMP2 and MMP9 are members of the matrix metalloproteinase (MMP) family of proteolytic enzymes, and a previous study reported that MMPs are considerably elevated in malignant tumors." (PMID 29805736, 2018). "In the present study, two kisspeptin phosphinic peptides were designed and synthesized, and their ability to induce phosphorylation of ERK1/2 through kisspeptin receptor and their inhibition on MMP-2 and MMP-9 whose activity correlates with cancer metastasis were assessed." (PMID 29614094, 2018). "A correlation of MMP2/9 and CD44 expression was established in cancer cell line models suggesting that inhibiting the CD44-MMP axis might provide therapeutic targets for suppressing metastasis." (PMID 29747682, 2018). "Besides, matrix metalloproteinases (MMPs) including MMP2 and MMP9 also contribute to the invasive and metastatic phenotypes of a variety of cancer cells by degrading the extracellular matrix and other barriers." (PMID 29300772, 2018). "MMP-2 and MMP-9 are highly expressed in malignant tumors with a high metastatic capacity." (PMID 29794990, 2018). "While Western blotting, zymography, and Enzyme-Linked Immunosorbent Assays (ELISA) can be used to measure the amount of MMP-2 activity, it is not possible to visualize the dynamic MMP-2 activities of cancer cells using these techniques." (PMID 29466303, 2018). "To determine whether MMPs play an important role in STS-mediated cancer cell invasion, we investigated the expression of MMP-1, MMP-2, and MMP-9 mRNA in PC-3 or HeLa cells expressing STS after exposure to STX-64." (PMID 28977889, 2017). "The high levels of MMP2 and MMP9, which are important factors in extracellular matrix remodeling, are evidence of good biomimicry, and we can conclude that the fibroblast-layered microtissue better represents cancer tissues than the monocultured microtissue." (PMID 29112150, 2017). "Secondly, the expression of MMP-2 and MMP-9 can also be regulated by ERK1/2 in cancer cells." (PMID 28424406, 2017). "Like MMP2, PIK3CA and AKT1 play important roles in cancer cell migration and metastasis." (PMID 29322935, 2017). "RT–PCR analyses revealed lower levels of MMP2, MMP9, and uPA mRNA in daurinol-treated cancer cells." (PMID 28915654, 2017).
cancer (continued). "TIMP-1, TIMP-2, MMP-2 and MMP-9 are cancer metastasis related expressions, Res and PA combination could raise TIMP-1, TIMP-2 and reduce MMP-2 and MMP-9 expressions in HepG2 cancer cells, and these effects were stronger than only PA treatment." (PMID 28978315, 2017). "BITC, PEITC, and SFN suppressed both MMP-9 activity and migration of cancer cells regardless of MMP-2 activity status." (PMID 28969043, 2017). "In addition, FAK activation further leads to secretion of MMPs such as MMP-2 and MMP-9, which are involved in the degradation of ECM to facilitate cancer cell metastasis." (PMID 28915654, 2017). "The inhibition of MMP-2 and MMP-9 enzyme activities can prevent of cancer metastasis." (PMID 29285298, 2017). "Matrix metalloproteinases (MMPs) such as MMP-2 and MMP-9 play critical roles in the proteolytic degradation of the extracellular matrix (ECM) surrounding the primary tumor, which is required for the migration and invasion of cancer cells." (PMID 28481901, 2017). "In our study, we have also found that the BBM-NPs can effectively inhibit migration and invasion which might be due to reduced MMP-2/MMP-9 activation and VEGF expression in highly metastatic cancer cells in comparison to native BBM." (PMID 28724926, 2017). "MMP family members, especially MMP-2 and MMP-9, are known to digest collagen, gelatin and other components of the extracellular matrix (ECM), resulting in the breakdown of the barriers of cancer cells." (PMID 28729634, 2017). "When CM was analyzed by gelatin and plasminogen zymography, reduced levels of 72/92 kDa (MMP2/MMP9) and 70/45kDa (tPA/uPA) zone clearing activity were detected from daurinol treated MDA-MB-231 and A549 cancer cells compared to the control in a concentration-dependent manner." (PMID 28915654, 2017). "For the non-cancer diseases (N), only two genes (VEGFA and MMP2) can be mapped to this pathway." (PMID 28340554, 2017). "In addition, GPER also activates cAMP and PIP2 signaling, inducing expression of matrix metalloproteinase 2 (MMP2) and MMP9, which, in turn, promote cancer metastasis." (PMID 28439256, 2017). "MMP-2 can degrade ECM molecules, thereby facilitating cancer cell invasion." (PMID 28915588, 2017). "The MMP2 gene expression followed exactly the opposite trend of SRD5A2, and this was consistent with data described also by other researches, where exogenous expression of SRD5A2 reduces the cell migration/invasion in cancer cells." (PMID 28489571, 2017). "Furthermore, MMP-2 and MMP-9 can break down collagen, which is an important component of the basement membrane, and are significantly related to cancer invasion and metastasis." (PMID 28152502, 2017). "HPßCD-HET0016 treatment was also able to significantly decrease the protein expression of EGF, Fas, and SDF-1α in conjunction with the reduced levels of MMP-2 and -9, and the granulocytic MDSC population result in an overall attenuation of migratory and invasive properties of cancer cells." (PMID 28609459, 2017). "If any effect of Apixaban exists on a cancer cell membrane "FXa-like" protease, this is not mediated by MMP2 and MMP9." (PMID 29023465, 2017). "OPN binding to CD44 or integrins has been known to up-regulate the expression or activation of various downstream molecules such as MMP-2, MMP-9, cyclooxygenase-2, and vascular endothelial growth factor, which are essential for determining the oncogenic potential of various cancers." (PMID 29254164, 2017). "We speculate that TM4SF1-mediated upregulation of uPA, MMP-2, and MMP-9 increases the degradation of ECM by cancer cells, leading to invasion and metastasis of cancer cells." (PMID 27153056, 2016). "p38α also induces the expression of MMP1, MMP2, MMP9 and MMP13 in other types of cancer." (PMID 27286263, 2016). "Notably, MMPs [such as MMP-2 (gelatinase A) and MMP-9 (gelatinase B)] have been reported to degrade type IV collagen to facilitate cancer cell invasion and metastasis." (PMID 27349797, 2016).